ELOVL6 (ELOVL fatty acid elongase 6)
Diseases named in the same sentence as ELOVL6 in open-access papers (continued):
Sharing a sentence is not in itself a finding about the gene and the disease.
hepatocellular carcinoma (12 papers, 2011 to 2026). A malignant tumor that arises from hepatocytes. "ELOVL6 is implicated in metabolic reprogramming in several cancer types, such as colorectal cancer and hepatocellular carcinoma." (PMID 37981715, 2023). "Among them, ELOVL6 is associated with the poor prognosis of patients with hepatocellular carcinoma, triple-negative breast cancer, and colorectal cancer." (PMID 36818393, 2023). "ELOVL6 is overexpressed in NASH-associated hepatocellular carcinoma and in acute myeloid leukemia, while ELOVL7 is overexpressed in prostate cancer cells." (PMID 26862848, 2016). "Likewise, a study on hepatocellular carcinomas indicated that patient tumors that were highly expressive of ELOVL6 were associated with shorter durations of overall survivability, while in a mouse-model inhibition of ELOVL6 increased survivability." (PMID 34421820, 2021). "Patients with glioblastoma multiforme and hepatocellular carcinoma have poor prognosis due to high ELOVL6 levels." (PMID 39457531, 2024). "Knockdown of ELOVL6 expression inhibited hepatocellular carcinoma cell proliferation in vitro and in vivo." (PMID 36532007, 2022). "Meanwhile, a positive correlation was observed between high ELOVL6 expression and the survival of patients with hepatocellular carcinoma." (PMID 36532007, 2022). "Phosphorylation of Akt is activated by insulin stimulation, and Elovl6 suppresses Akt phosphorylation in the presence of insulin in mouse hepatoma cells." (PMID 29700319, 2018). "In hepatocellular carcinoma, knockdown of Elovl6 in HCC cells reduced cell proliferation and Akt activation, as well as sensitivity to fatty acids." (PMID 37981715, 2023). "In summary, the highly conserved gga-miR-221-5p was proved to directly target ELOVL6 and SQLE mRNAs to affect the level of intracellular triglyceride and total cholesterol in LMH chicken hepatoma cells." (PMID 32120850, 2020). "Using human hepatoma Huh7 cells, we found that palmitic acid (PA), but not oleic acid (OA), induced a transient upregulation of ELOVL6 mRNA expression at 24 h, which diminished by 48 h." (PMID 41768220, 2026).
steatosis (11 papers, 2010 to 2025). Increased lipid within the cytoplasm of cells. "Further, the expression of hepatic steatosis-related genes Scd1 and Fasn in any of the groups, while that of Elovl6 was higher in ND + MP 5000 μg/L mice than in ND mice." (PMID 39600697, 2024). "One example represents the fatty acid elongase ELOVL6, which contributes to the progression of pre-tumorous conditions, such as steatosis and steatohepatitis." (PMID 31717307, 2019). "Moreover, depletion of the palmitate elongase, Elovl6, attenuated NASH progression in mice, and expression of Elovl6 was positively correlated with severity of steatosis and liver injury in human NASH patients." (PMID 26289793, 2015). "In fact, the activities of fatty acid desaturase 1 (FADS1) and elongase 6 (ELOVL6) were decreased in MASH patients, and their role in the progression of simple steatosis to MASH is a subject currently under intense investigation." (PMID 40649925, 2025). "We also find that ZFD induces steatosis in GF mice, possibly due to low PUFA levels, which can increase SREBP-1c activity and decrease PPARα activity, leading to increased expression of lipogenic genes like Elovl6 and Scd1 and a shift toward lipid synthesis." (PMID 40345386, 2025).
diabetes (10 papers, 2011 to 2023). "In fact, in a recent study of the db/db mouse model of diabetes, loss of ELOVL6 alters insulin sensitivity and the expression of ER stress genes." (PMID 30081392, 2018). "The experimental results together with those reported here suggest that the ELOVL6 gene could be a future therapeutic target in the treatment of diabetes and related disorders." (PMID 21701577, 2011). "Although it has been proved that ELOVL6 is a key enzyme in intracellular lipid metabolism and is closely associated with fatty liver and diabetes, there are no systematic and comprehensive researches of the effects of Elovl6 in lipid metabolism and glucose metabolism." (PMID 32325903, 2020). "The expression of Elovl6 did not correlate significantly with diabetes mellitus, body mass index (BMI), hepatitis B, or hepatitis C." (PMID 29700319, 2018). "The ELOVL5 expression, compared to ELOVL6, is not altered by SREBP-1c, glucose, or diabetes." (PMID 36291290, 2022).
Hyperinsulinemia (7 papers, 2010 to 2020). An increased concentration of insulin in the blood. "Both wild-type and Elovl6−/− mice manifested pancreatic islet hyperplasia that parallels the development of hyperinsulinemia." (PMID 25281760, 2014). "In the present study we made a novel observation of ELOVL6 down-regulation in the obese insulin resistant as compared to the lean insulin-sensitive group in hyperinsulinemia." (PMID 22471940, 2012). "This is the first study to examine the association between genetic variation of the ELOVL6 gene and insulin sensitivity in humans, measured by HOMA as well as hyperinsulinemia at 120 minutes after the OGTT." (PMID 21701577, 2011). "Furthermore, differences were observed in genes contributing to fatty acid, cholesterol and triglyceride metabolism (FATP2, ELOVL6, PNPLA3, SREBF1) and in genes involved in regulating lipolysis (ANGPTL4) between the insulin-resistant and -sensitive subjects especially during hyperinsulinemia." (PMID 22471940, 2012).
liver cancer (7 papers, 2018 to 2023). An epithelial or non-epithelial malignant neoplasm that arises from the liver. "Taken together, our results indicate that Elovl6 enhances oncogenic activity in liver cancer and is associated with poor prognosis in patients with HCC." (PMID 29700319, 2018). "Elovl6 enhances liver cancer oncogenic function and is linked with substandard HCC prognosis." (PMID 38186579, 2023). "Although here, we show that silencing of Elovl6 expression changed cell morphology and sensitivity to fatty acids in liver cancer cells, the determination of the oncogenic role of Elovl6 remains challenging." (PMID 29700319, 2018). "Knockdown of Elovl6 was verified with RT-PCR analysis in mouse ML-1 liver cancer cells infected with Ad.shElovl6 at 10 multiplicities of infection (MOI)." (PMID 29700319, 2018). "In addition, ELOVL6 was inconsistent with the results of other researchers.They found that ELOVL6 enhanced oncogenic activity in liver cancer and indicated poor prognosis in patients with HCC, whereas the results of ours showed no significance." (PMID 35912257, 2022). "The status of ELOVL6 in cancer is less clear, as both increased and decreased expression have been reported to correlate negatively with cancer progression and patient survival in breast or liver cancer." (PMID 34206240, 2021). "Specific to the luminal A comparison was the gene CCND1 (oncogene; breast and pan-cancer), the second most interconnected after ESR1 (oncogene; breast and pan-cancer), while ELOVL6 (oncogene; liver cancer) was the most interconnected unique gene within the luminal B vs TNBC network." (PMID 32605588, 2020). "ELOVL6 was previously identified as a negative clinical predictor of liver cancer, and its knockdown was reported to decrease cancer progression in mice." (PMID 36364557, 2022).
atherosclerosis (5 papers, 2016 to 2025). A disease characterized by the build-up of fatty material and calcium deposition in the arterial wall resulting in partial or complete occlusion of the arterial lumen. "Further studies are needed to verify our hypothesis that activation of AMPK/KLF4 signaling by loss of Elovl6 is protective against atherosclerosis by using double knockout mice of Elovl6 and apoE." (PMID 27881420, 2016). "The study began with our initial observation that the Elovl6-/- mice often suffered from growth retardation despite their significant metabolic advantages in insulin sensitivity and atherosclerosis." (PMID 27467521, 2016). "Elovl6 knockout mice showed a marked resistant to diet-induced hyperinsulinemia, atherosclerosis, and steatohepatitis presumably due to the altered fatty acid composition in the liver and macrophages, respectively." (PMID 27467521, 2016). "The modulation of Elovl6‐mediated cellular processes may provide an intriguing approach for tackling atherosclerosis and postangioplasty restenosis." (PMID 27881420, 2016).
metabolic syndrome (5 papers, 2013 to 2022). A cluster of metabolic risk factors for CARDIOVASCULAR DISEASES and TYPE 2 DIABETES MELLITUS. "Both ELOVL1 and ELOVL6 are biomarkers associated with an increased risk of NAFLD in the HIV-negative population with metabolic syndrome." (PMID 35807127, 2022).
nonalcoholic steatohepatitis (5 papers, 2016 to 2025). "Its related isoforms, namely ELOVL6, have been found to have a bi-directional relationship with the pathogenesis of non-alcoholic steatohepatitis in humans and mice." (PMID 40040391, 2025). "Also expression of fatty acid elongases 6 (ELOVL6), which has been described as critical promoter of nonalcoholic steatohepatitis, was reduced by 5-FU." (PMID 28055957, 2017).
type 2 diabetes (5 papers, 2016 to 2025). "Notably, the ratio of stearic acid to palmitic acid was inversely correlated with type 2 diabetes, suggesting that a lower 5-year risk of type 2 diabetes was linked to higher expression of the Elovl6 enzyme." (PMID 39940428, 2025).
glioblastoma (4 papers, 2023 to 2024). The most malignant astrocytic tumor (WHO grade IV). "We have demonstrated a positive correlation between the expression of SLC27A1 and SLC27A3 and the expression of ELOVL6 in both the glioblastoma tumor and the peritumoral area." (PMID 37239243, 2023). "There is some evidence that the knockdown of ELOVL6 inhibits migrations of some cells, like normal vascular smooth muscle cells or glioblastoma multiforme cells." (PMID 38139442, 2023). "In murine glioblastoma tumors, Elovl6 expression is increased." (PMID 37046844, 2023). "Taking into account all patients, the expression of Elovl6 does not change in the glioblastoma tumor compared to the nontumor brain tissue." (PMID 37046844, 2023). "Expression data for ELOVL1, ELOVL3, ELOVL6, SCD, and FADS2 were obtained from raw data published in our previous papers, where we examined the expression of elongases and desaturases in glioblastomas." (PMID 37239243, 2023). "According to GEPIA, high expression of Elovl6 does not affect patient prognosis in glioblastoma." (PMID 37046844, 2023).
colon cancer (3 papers, 2020 to 2023). "Expression of lipogenic genes (ELOVL6 and SCD1) in colon cancer was also positively associated with colon malignancy (for both genes, p < 0.001)." (PMID 32144313, 2020). "The protein levels of glucose transporter (GLUT1 and GLUT2) and mRNA levels of ChREBP regulated lipogenic gene (ELOVL6 and SCD1) showed a similar expression pattern, indicating increased glycolysis and lipogenesis with the progress of colon cancer." (PMID 32144313, 2020). "Here, we did not observe an upregulation of either enzyme (instead, ELOVL6 expression decreased in colon tumors)." (PMID 34206240, 2021).
colorectal cancer (3 papers, 2023 to 2025). A primary or metastatic malignant neoplasm that affects the colon or rectum. "Apatinib might also enhance ELOVL6/ACSL4-mediated ferroptosis in colorectal cancer cells." (PMID 38347631, 2024). "Survival analysis of differentially expressed longevity-related genes in colorectal cancer found that the expression of 18 genes, including RAD50, ELOVL6, and BEND3, had a greater impact on patient survival." (PMID 40426913, 2025).
dermatitis (3 papers, 2018 to 2023). An inflammatory process affecting the skin. "Elovl6 deficiency accelerated tape stripping-triggered keratinocyte death, which possibly not only caused the skin barrier dysfunction but also increased the DAMPs release from the dead keratinocytes, thus exacerbating dermatitis." (PMID 30518914, 2018). "Mice deficient in Elovl6 showed higher levels of cis-vaccenic acid (CVA) in the epidermis and severe skin inflammation induced by mechanical damage due to tape stripping than did wild-type mice." (PMID 30518914, 2018). "To investigate the role of Elovl6 in mechanical damage-induced skin inflammation, we established a mouse model of dermatitis by using repeated tape stripping." (PMID 30518914, 2018). "Together, these results suggest that Elovl6 suppressed mechanical damage-induced keratinocyte death and skin inflammation." (PMID 30518914, 2018). "Our results demonstrate that Elovl6 regulates mechanical damage—triggered keratinocyte death and the subsequent dermatitis." (PMID 30518914, 2018). "In the current study, we examined whether long-chain fatty-acid composition regulated by Elovl6 is involved in mechanical damage-induced skin inflammation." (PMID 30518914, 2018). "Together, these results suggest that Elovl6 suppresses mechanical damage-induced skin inflammation." (PMID 30518914, 2018). "The expression of ELOVL4 substantially decreased by 76.2 ± 9.6% in FAg-induced dermatitis compared with that in control mouse skin, and the expression of the other ELOVL isozymes except for ELOVL3 also significantly decreased, with the highest inhibition in ELOVL6." (PMID 30838224, 2019).
pulmonary fibrosis (3 papers, 2016 to 2025). Chronic progressive interstitial lung disorder characterized by the replacement of the lung tissue by connective tissue, leading to progressive dyspnea, respiratory failure, or right heart failure. "During pulmonary fibrosis, ELOVL6 expression decreases, favoring palmitic acid accumulation." (PMID 38612561, 2024).
acute myeloid leukemia (2 papers, 2016 to 2023). Acute myeloid leukemia (AML) is a group of neoplasms arising from precursor cells committed to the myeloid cell-line differentiation. "In acute myeloid leukemia ELOVL6 appears to be activated by a novel chromosome rearrangement causing the activation of both EGF and ELOVL6." (PMID 26862848, 2016). "Here, we report that ELOVL6 is essential for hematopoietic stem cell (HSC) engraftment after bone marrow (BM) transplantation and that it blocks acute myeloid leukemia (AML) development in a mouse model." (PMID 36890291, 2023).
glioma (2 papers, 2022). A benign or malignant brain and spinal cord tumor that arises from glial cells (astrocytes, oligodendrocytes, ependymal cells). "On the other hand, Pathology Atlas showed that a higher ELOVL6 expression in glioma tumors is associated with a worse prognosis." (PMID 36291290, 2022).
insulinoma (2 papers, 2022 to 2023). "After the knockdown of ELOVL6 decreased the level of C18:0, C18:1n − 9, an increased level of C16:1n − 7 was observed in the skeletal muscle cell line and insulinoma cell line." (PMID 38139442, 2023). "Knockdown of ELOVL6 in rat insulinoma cell lines and mice demonstrated that ELOVL6 is required for monounsaturated fatty acid synthesis." (PMID 35498736, 2022).
prediabetes (2 papers, 2016 to 2022). "This study demonstrates that LJF and CGA exert hypoglycemic and lipid modulation capacity to prevent prediabetes may through the CTRPs-AdipoRs-AMPK/PPARα axes and promoting ELOVL6 protein expression." (PMID 36313074, 2022).
prostate carcinoma (2 papers, 2016 to 2020). A carcinoma that arises from epithelial cells of the prostate gland. "However, EPB41L5 and SERINC3 had a high rank based on mutational burden and CNVs, ELOVL6 was annotated as an oncogene in prostate cancer, and PPM1H has been proposed to be an oncogene, due to its relation to PPM1D (a well-studied oncogene in breast, ovarian, and brain cancers)." (PMID 32605588, 2020). "A high level of ELOVL6 (oncogene in prostate cancer) has been proposed to be a marker of poor prognosis in BC, which is of great interest, as patients with luminal B type tumors generally have poorer outcomes than those with luminal A types." (PMID 32605588, 2020).
asthma (1 paper, 2025). "Recently, it has been indicated that the elongation of very-long-chain fatty acid protein 6 (ELOVL6), a regulating enzyme for the elongation of saturated and monounsaturated fatty acids with C12 to C16 and those with C18, may be involved in asthma." (PMID 40001485, 2025). "The expression of ELOVL6 is enhanced in the bronchial epithelial cells of patients with severe asthma, and both Th2 and non-Th2 inflammation is enhanced with increases in ceramides and S1P in ELOVL6-deficiency mice, suggesting that ELOVL6 may be a novel target molecule for the treatment of asthma." (PMID 40001485, 2025).
bladder cancer (1 paper, 2018). "Relatively little information is available regarding SCD1, SREBP1, and ELOVL6 (encoding elongase 6) expression in human bladder cancer." (PMID 29396722, 2018). "Additionally, the association between the SCD1 mRNA level and the expression of SREBP1 and ELOVL6 remains to be elucidated in human bladder cancer." (PMID 29396722, 2018). "In the T2–T4 stages of bladder cancer, a significant increase in ELOVL6 mRNA was found (P = 0.036)." (PMID 29396722, 2018). "As with SCD1, a progressive increase in the level of ELOVL6 mRNA was found in bladder cancer." (PMID 29396722, 2018). "Finally, we have shown the upregulation of SREBP1 and ELOVL6 in human bladder cancer." (PMID 29396722, 2018).
cervical carcinoma (1 paper, 2017). A carcinoma arising from either the exocervical squamous epithelium or the endocervical glandular epithelium. "We conclude that, in cervical carcinoma HTB-34 cells, CA modestly activates AMPK, while Met exerts its effect on FA biosynthesis by downregulation of several enzymes involved in the de novo synthesis of long unsaturated FA, such as ACLY, FAS, ELOVL6, and SCD1." (PMID 28230778, 2017).
colon adenocarcinoma (1 paper, 2022). "While low expression of SUCLG2 (p < 0.001), PTGR1 (p = 0.001), ELOVL6 (p = 0.013) and CPT2 (p < 0.001) were correlated with poor overall survival of colon adenocarcinoma patients." (PMID 36568396, 2022). "Results showed increased expression of ENO3, MORC2, SUCLG2 and ELOVL6, and decreased expression of CPT2 in all examined colon adenocarcinoma cell lines." (PMID 36568396, 2022). "Moreover, qRT-PCR revealed upregulated expression of ENO3, MORC2, SUCLG2 and ELOVL6, and downregulated expression of CPT2 in all examined colon adenocarcinoma cell lines." (PMID 36568396, 2022).
colorectal adenocarcinoma (1 paper, 2023). The most common type of colorectal carcinoma. "Changes in the expression levels of ELOVL4 and ELOVL6 observed in our in vitro model of colorectal adenocarcinoma corresponded with changes observed in patients’ CRC tissue." (PMID 38139442, 2023).
colorectal tumors (1 paper, 2021). "A recent study has suggested that colorectal tumors exhibit significantly higher levels of 22-, 24-, and 26-carbon FAs, as well as higher levels of ELOVL1 and ELOVL6 enzymes." (PMID 34206240, 2021).
dysplasia (1 paper, 2023). A usually neoplastic transformation of the cell, associated with altered architectural tissue patterns. "Finally, we utilized human oral tissue, which is common in head and neck tissue, to investigate the expression of ELOVL6 among normal oral mucosa, dysplasia, and OSCC tissues by IHC." (PMID 36818393, 2023). "ELOVL6 expression in the OSCC II/III group was significantly higher than that in the other three groups (normal, dysplasia, and OSCC I), and OSCC patients with high ELOVL6 expression had poorer survival than those with low ELOVL6 expression." (PMID 36818393, 2023). "The rate of high ELOVL6 expression was 45.5% in the OSCC II/III group and 16.7%, 5.4%, and 18.4% in the normal, dysplasia, and OSCC I groups, respectively, and the rate of high ELOVL6 expression in the OSCC II/III group was significantly higher than that in the other three groups." (PMID 36818393, 2023).